MIR3184 (microRNA 3184)
Synonyms: hsa-mir-3184
Gene: MicroRNA gene on chromosome 17 (30,117,086 to 30,117,160, reverse strand). Ensembl gene ENSG00000284399.
Gene Ontology:
Biological process: miRNA-mediated post-transcriptional gene silencing
Cellular component: RISC complex
Homologues: Orthologues: chimpanzee MIR3184 (100% identical).